PARL (presenilin associated rhomboid like)
Description:
Required for the control of apoptosis during postnatal growth. Essential for proteolytic processing of an antiapoptotic form of OPA1 which prevents the release of mitochondrial cytochrome c in response to intrinsic apoptotic signals (By similarity). Required for the maturation of PINK1 into its 52kDa mature form after its cleavage by mitochondrial-processing peptidase (MPP). Promotes cleavage of serine/threonine-protein phosphatase PGAM5 in damaged mitochondria in response to loss of mitochondrial membrane potential. Mediates differential cleavage of PINK1 and PGAM5 depending on the health status of mitochondria, disassociating from PINK1 and associating with PGAM5 in response to mitochondrial membrane potential loss. Required for processing of CLPB into a form with higher protein disaggregase activity by removing an autoinhibitory N-terminal peptide. Promotes processing of DIABLO/SMAC in the mitochondrion which is required for DIABLO apoptotic activity. Mediates STARD7 processing which regulates STARD7 location between mitochodria and cytosol. Also required for cleavage of TTC19. Promotes changes in mitochondria morphology regulated by phosphorylation of P-beta domain.
Synonyms: PSARL; PRO2207; PSARL1; RHBDS1; PSENIP2
Tractability: Small molecule: a high-quality ligand is known. Antibody: UniProt predicts a signal peptide or a membrane-spanning region. PROTAC: ubiquitination databases record sites on it; its protein half-life has been measured; a small molecule that binds it is known.
Target class: Enzyme; Hydrolase
Gene: Protein-coding gene on chromosome 3 (183,829,271 to 183,884,933, reverse strand). Ensembl gene ENSG00000175193.
Subcellular location: Mitochondrion inner membrane; Nucleus (P-beta)
Subcellular location (Human Protein Atlas): Mitochondria
Pathways (Reactome):
Transport of small molecules: Processing of SMDT1
Gene Ontology:
Molecular function: endopeptidase activity; protein binding; serine-type endopeptidase activity
Biological process: membrane protein proteolysis; protein processing; proteolysis; regulation of establishment of protein localization to mitochondrion; regulation of mitochondrion organization; regulation of proteolysis; regulation of reactive oxygen species metabolic process; regulation of mitophagy; mitochondrial fusion; negative regulation of intrinsic apoptotic signaling pathway; negative regulation of release of cytochrome c from mitochondria
Cellular component: mitochondrial inner membrane; mitochondrion; nucleus; membrane
Genetic constraint (gnomAD): Loss-of-function variants: 25 observed, 27.85 expected, observed/expected ratio (o/e) 0.9, 90% interval 0.65 to 1.25. The upper end of that interval is the gene's LOEUF score, 1.25, which puts it in group 5 of 6, group 1 being the genes least tolerant of losing a copy. Missense variants: 328 observed, 326.58 expected, observed/expected ratio (o/e) 1, 90% interval 0.92 to 1.1. Synonymous variants: 124 observed, 113.39 expected, observed/expected ratio (o/e) 1.09, 90% interval 0.94 to 1.27.
Homologues: Orthologues: chimpanzee PARL (99% identical), pig PARL (94% identical), mouse Parl (91% identical), rat Parl (89% identical), macaque PARL (89% identical), guinea pig PARL (89% identical), dog PARL (89% identical), tropical clawed frog parl (62% identical), zebrafish parlb (60% identical), zebrafish parla (54% identical), Drosophila melanogaster rho-7 (39% identical), Caenorhabditis elegans rom-5 (32% identical). Paralogues in human: RHBDF1 (22% identical), RHBDF2 (20% identical), RHBDL3 (15% identical), RHBDL2 (13% identical), RHBDL1 (13% identical).
Diseases named in the same sentence as PARL in open-access papers:
PARL is named in the same sentence as 38 diseases in open-access papers, as found by Europe PMC text mining. Sharing a sentence is not in itself a finding about the gene and the disease. The quoted sentences say what the papers report.
Parkinson disease (12 papers, 2017 to 2025). A progressive degenerative disorder of the central nervous system characterized by loss of dopamine producing neurons in the substantia nigra and the presence of Lewy bodies in the substantia nigra and locus coeruleus. "PARL, a serine protease previously linked to Parkinson's disease, was downregulated and also uniquely identified in our meta‐analysis." (PMID 40042520, 2025). "PARL has been associated with various human disorders such as Parkinson’s disease, Leber hereditary optic neuropathy, and type 2 diabetes, albeit with some controversy." (PMID 37505079, 2023). "This suggests that if PARL mutations are a genetic cause of Parkinson′s disease, then they are likely to be extremely rare." (PMID 35163221, 2022). "The role of a gene, which interacts with PTEN-induced putative kinase in mitochondrial homeostasis and during early-onset Parkinson disease, called presenilin-associated rhomboid-like (PARL), was investigated." (PMID 29857474, 2018). "It has beenimplicated in the pathogenesis of Parkinson’s disease, butits investigation as a possible therapeutic target is challengingin this context because genetic deficiency of PARL may result in compensatorymechanisms." (PMID 36540942, 2023). "The cascade of altered PARL function is associated with induction of Parkinson disease." (PMID 33426505, 2020). "Single nucleotide polymorphisms in PARL represented a rare cause of Parkinson disease." (PMID 29857474, 2018). "Besides, PARL mutation may partially contribute to the formation of Lewy bodies and is associated with the pathogenesis of Parkinson’ disease." (PMID 40013375, 2025). "Presenilins-associated rhomboid-like protein, mitochondrial (PARL) is a mitochondrial protease that cleaves PINK1, implicated in Parkinson’s disease and decreased activity could be associated with increased mitophagy through Parkin." (PMID 33986742, 2021). "Indeed, PARL-activated Skd3 solubilizes α-synuclein fibrils connected to Parkinson’s disease." (PMID 32573439, 2020). "Importantly, this study discloses a wayof pharmacologically blocking PARL to boost PINK1/Parkin-dependentmitophagy, whose enhancement is explored as a therapeutic approachfor the treatment of Parkinson’s disease." (PMID 36540942, 2023). "Here, using microscopy, kinetic analysis, and molecular dynamics simulations, we analyzed three Parkinson’s disease–associated TM mutations; PINK1-C92F, PINK1-R98W, and PINK1-I111S, and found that mitochondrial localization and cleavage by the PARL protease were not significantly impaired." (PMID 39909370, 2025).
myopia (3 papers, 2008 to 2010). "Furthermore, single nucleotide polymorphisms in the mitofusin-1 (MFN1) and presenilin associated rhomboid-like (PSARL) genes are among the clustering peak showing a genetic association with myopia that was mapped to 3q26 (MYP8 locus)." (PMID 20208987, 2010). "Moreover, a recent genome-wide linkage study followed by a fine-scale association mapping identified a myopia susceptibility gene locus containing the PARL gene which inhibits the mitochondrial pathway of apoptosis by interaction with OPA1." (PMID 19779542, 2009).
dominant optic atrophy (2 papers, 2014 to 2021). "Finally, PARL is a mitochondrial protease, which cleaves, among others, OPA1 and PINK1, genes responsible for dominant optic atrophy and familial Parkinson’s disease." (PMID 24369379, 2014).
Insulin resistance (2 papers, 2014 to 2015). Increased resistance towards insulin, that is, diminished effectiveness of insulin in reducing blood glucose levels. "Reduced PARL levels correlate with mitochondrial abnormalities in obesity and are linked with insulin resistance." (PMID 26258540, 2015).
ischemia (2 papers, 2008 to 2021). A hypoperfusion of the BLOOD through an organ or tissue caused by a PATHOLOGIC CONSTRICTION or obstruction of its BLOOD VESSELS, or an absence of BLOOD CIRCULATION. "Activation of rhomboid intramembrane protease (PARL) may explain the cleavage of OPA1 into truncated forms observed in the present study following ischemia." (PMID 19122832, 2008).
Leigh syndrome (2 papers, 2023 to 2024). A progressive neurological disease defined by specific neuropathological features associating brainstem and basal ganglia lesions. "In our previous study, we described PARL-deficient mice as a novel model of mitochondrial encephalopathy resembling Leigh syndrome, one of the most common and severe mitochondrial diseases." (PMID 37505079, 2023). "PARL-deficient mice appear clinically normal until around 6 weeks of age, after which they develop a progressive necrotizing encephalomyelopathy resembling Leigh syndrome with death before the age of 8 weeks." (PMID 37505079, 2023). "A previous study found that mutant mice that lack an enzyme, called PARL, display symptoms that are similar to those observed in humans with Leigh syndrome." (PMID 37505079, 2023). "PARL is described to affect the assembly of complex III through its substrate TTC19 and to regulate coenzyme Q synthesis through COQ4, causing respiratory chain deficits leading to Leigh syndrome-like neuronal degeneration." (PMID 38182793, 2024).
pancreatic cancer (2 papers, 2023 to 2025). "Based on the proteomic data of 140 pancreatic cancer cases, there was a significant positive association between STOML2 and PARL at the protein level (P = 0.02, R = 0.24)." (PMID 36906621, 2023). "In conclusion, our study found that STOML2 could repress PINK1-induced mitophagy by directly stabilizing PARL, thus inhibiting pancreatic cancer chemoresistance." (PMID 36906621, 2023). "In both PANC1 and BxPC3 cells, the STOML2 antibody could also pull down PARL, which suggested that STOML2 could directly bind and stabilize PARL in pancreatic cancer cells." (PMID 36906621, 2023). "In conclusion, STOML2 could stabilize PARL and promote PINK1 degradation, which represses mitophagy and ultimately reduces chemoresistance in pancreatic cancer." (PMID 36906621, 2023).
amyotrophic lateral sclerosis (1 paper, 2025). Amyotrophic lateral sclerosis (ALS) is a neurodegenerative disease characterized by progressive muscular paralysis reflecting degeneration of motor neurons in the primary motor cortex, corticospinal tracts, brainstem and spinal cord. "Beyond PD and DLB, PARL dysfunction has been implicated in amyotrophic lateral sclerosis (ALS)." (PMID 41015904, 2025).
Atrophy (1 paper, 2022). Any weakening or degeneration, especially through lack of use. "The phenotype of Parl−/− or PARL-deficient mice is characterized by progressive multisystemic atrophy from their fourth postnatal week, eventually resulting in cachectic death." (PMID 35163221, 2022).
cardiomyopathy (1 paper, 2021). A disease of the heart muscle or myocardium proper. "PARL has been implicated in regulating the mitochondrial responses to stress, including membrane depolarization and increased reactive oxygen species, and dysregulation of PARL substrates has been implicated in cardiomyopathy and cardiac development." (PMID 34314685, 2021).
Cognitive impairment (1 paper, 2025). Abnormal cognition is characterized by deficits in thinking, reasoning, or remembering. "As expected, both PARL overexpression and PGAM5 knockdown could rescue the Meth‐induced cognitive impairments." (PMID 40013375, 2025).
colon cancer (1 paper, 2023). "We also deleted PARL and STARD7 in the colon cancer cell line HCT116." (PMID 36658222, 2023).
diabetes (1 paper, 2022). "Moreover, screening performed on 1031 North Americans found that the presence of a Leu262Val polymorphism in PARL was associated with increased plasma insulin concentration, making it a risk factor for diabetes." (PMID 35163221, 2022).
gastric cancer (1 paper, 2025). A primary or metastatic malignant neoplasm involving the stomach. "Similarly, NPR1 interacts with PARL, stabilizing it and contributing to cisplatin resistance in gastric cancer cells." (PMID 40630134, 2025).
glaucoma (1 paper, 2009). Increased pressure in the eyeball due to obstruction of the outflow of aqueous humor. "The objective of this study was to investigate association of several genes that have not been subject to an association study with glaucoma cases so far but might be functionally linked to glaucoma pathogenesis (RDX, SNX16, MFN1, MFN2, PARL, SOD2)." (PMID 19754948, 2009).
glioblastoma (1 paper, 2022). The most malignant astrocytic tumor (WHO grade IV). "The mitochondrial damage caused glioblastoma cells to undergo autophagy preferentially by downregulating the expression of PARL and changing the ratio of BECN1/Bcl‐2 and the process of mitophagy was regulated by the PI3K/Akt/MAPK/mTOR/Ulk1 pathway." (PMID 34799992, 2022). "Western blotting showed that Dcf1 inhibited the expression of PARL, and the subcellular colocalization of BECN1‐Bcl‐2 in endoplasmic reticulum (ER) was not changed by Dcf1, suggesting that autophagy and apoptosis occurred in glioblastoma cells simultaneously." (PMID 34799992, 2022).
hearing defects (1 paper, 2021). "The influence of combined OPA1 and PARL mutations on the development of hearing defects in patients with ADOA warrants further investigation." (PMID 34573359, 2021).
leprosy (1 paper, 2016). Leprosy is a chronic infectious disease affecting primarily the skin and peripheral nervous system. "rs12631031 and rs7653061 in PARL were associated with leprosy and MB (dominant model, Padjusted < 0.05) at the genotypic level." (PMID 27876828, 2016). "We found that PARL SNP rs12631031 conferred a risk to leprosy (Padjusted = 0.019) and multibacillary leprosy (MB, Padjusted = 0.020) at the allelic level." (PMID 27876828, 2016). "We confirmed that common variants in PARL and PINK1 were associated with leprosy in patients underwent NGS." (PMID 27876828, 2016). "In summary, we found that common variants of the mitochondrial genes PARL and PINK1 would confer risk to leprosy per se and/or MB." (PMID 27876828, 2016). "Our results provided several lines of evidence showing that PARL and PINK1 confer genetic susceptibility to leprosy." (PMID 27876828, 2016). "In this study, we aimed to investigate the possible association of genetic variants in the PARL and PINK1 genes with leprosy in Han Chinese." (PMID 27876828, 2016). "In this study, we found that two mitochondrial genes, PARL and PINK1, conferred genetic susceptibility to leprosy per se and/or multibacillary leprosy." (PMID 27876828, 2016). "Among the analyzed tag SNPs in the PARL and PINK1 genes, three SNPs (rs12631031 and rs7653061 of PARL; rs4704 of PINK1) were associated with leprosy per se and/or MB." (PMID 27876828, 2016). "Together, our results showed that PARL and PINK1 genetic variants are associated with leprosy." (PMID 27876828, 2016). "We hypothesized that mitochondrial genes PARL and PINK1 would confer risk to leprosy." (PMID 27876828, 2016). "Furthermore, deep sequencing of the PARL, PINK1 and PARK2 genes in a relatively small sample identified two PARL variants (rs3732581 [p.V212L], rs13091 [p.H216]) and one PINK1 variant (rs45530340, [p.L63]) that were associated with leprosy." (PMID 27876828, 2016). "Furthermore, PARL and PINK1 could physically interact with each other and were involved in the highly connected network formed by reported leprosy susceptibility genes." (PMID 27876828, 2016). "We also sequenced the entire exons of PARL, PINK1 and PARK2 in 80 patients with a family history of leprosy by using the next generation sequencing technology (NGS)." (PMID 27876828, 2016). "Thirteen tag SNPs of PARL and PINK1 were analyzed in 3620 individuals with or without leprosy from China." (PMID 27876828, 2016).
normal tension glaucoma (1 paper, 2009). "Common variants of OPTN, PARL, MFN1 and MFN2 should be analysed in other cohorts to confirm their involvement in normal tension glaucoma." (PMID 19754948, 2009).
Obesity (1 paper, 2015). Accumulation of substantial excess body fat. "Maternal obesity and a high fat diet resulted in decreased expression of PARL in rats and it may play a role in metabolic programming." (PMID 26258540, 2015).
pterygium (1 paper, 2024). A wedge-shaped fibrovascular lesion arising from the bulbar conjunctiva and extending to the cornea. "As the NESs of the antioxidant and cytokines/chemokines indicated their positive enrichment in pterygiums in both Asian and European samples, GSTA1, PARL, and FOS might contribute to their upregulation in response to oxidative stress and DNA damage." (PMID 38732006, 2024).
type 2 diabetes (1 paper, 2018). "This suggests that PARL is an important candidate gene for the development of insulin resistance and type 2 diabetes." (PMID 30307158, 2018). "PARL mRNA expression in skeletal muscle is reduced in elderly subjects and patients with type 2 diabetes." (PMID 30307158, 2018).
cancer (5 papers, 2017 to 2024). A tumor composed of atypical neoplastic, often pleomorphic cells that invade other tissues. "Together it is conceivable that the loss of COX6B2 in PARL-deficient mice might be the cause of the decrease in complex IV proteins and complex IV activity, similar to what was described before in cancer cells." (PMID 38182793, 2024). "Proteases such as ubiquitin specific peptidase 30 (USP30), presenilin associated rhomboid like (PARL), and HtrA serine peptidase 2 (HTRA2) in the UPRmt can interact with mitophagic regulator PINK1-Parkin, and then inhibit mitophagy and maintain mitochondrial proteostasis in cancers." (PMID 30577555, 2018). "The study also demonstrated a correlation between PARL or STARD7 expression and cancer cell resistance to the ferroptosis inhibitor protein GPX4, suggesting that targeting PARL or STARD7 could be a potential strategy to disrupt ferroptosis and provide novel approaches for anticancer therapies." (PMID 37548939, 2024).
neurodegenerative disease (1 paper, 2024). A disorder of the central nervous system characterized by gradual and progressive loss of neural tissue and neurologic function. "This included two known proteins associated with MERCS, MFN2 and TOMM40, as well as neurodegenerative disease-associated genes such as WIPI2, CLASRP, BAG6, SOD1 and FUS which increase MERCS and MTCH2 and PARL which decrease MERCS." (PMID 38467609, 2024).
tumours (1 paper, 2023). "PARL and STARD7 may therefore represent promising targets to induce ferroptosis in tumours resistant to GPX4 inhibitors." (PMID 36658222, 2023).
PARL also shares sentences with these, for which no sentence is quoted: colorectal cancer (2 papers); brain ischemia (1); cardiac hypertrophy (1); cognitive decline (1); colitis (1); Infertility (1); malaria (1); male infertility (1); memory impairment (1); metabolic syndrome (1); Mitochondrial encephalopathy (1); Testicular atrophy (1); ulcerative colitis (1).